TCEAL5 (transcription elongation factor A like 5)
Description:
May be involved in transcriptional regulation.
Synonyms: WEX4
Tractability: PROTAC: its protein half-life has been measured.
Gene: Protein-coding gene on chromosome X (103,273,689 to 103,276,750, reverse strand). Ensembl gene ENSG00000204065.
Subcellular location: Nucleus
Subcellular location (Human Protein Atlas): Nucleoplasm
Gene Ontology:
Molecular function: protein binding
Cellular component: nucleus
Homologues: Orthologues: macaque TCEAL5 (96% identical), dog TCEAL3 (76% identical), dog TCEAL6 (75% identical), mouse Tceal5 (71% identical), rat Tceal5 (69% identical), mouse Tceal6 (69% identical), mouse Tceal3 (68% identical), rat Tceal3 (68% identical), rat Tceal6 (68% identical). Paralogues in human: TCEAL3 (88% identical), TCEAL6 (86% identical), TCEAL4 (50% identical), TCEAL2 (47% identical), TCEAL8 (20% identical), TCEAL1 (18% identical), TCEAL9 (17% identical), TCEAL7 (16% identical).
Diseases named in the same sentence as TCEAL5 in open-access papers:
TCEAL5 is named in the same sentence as 3 diseases in open-access papers, as found by Europe PMC text mining. Sharing a sentence is not in itself a finding about the gene and the disease. The quoted sentences say what the papers report.
gastric cancer (2 papers, 2013 to 2025). A primary or metastatic malignant neoplasm involving the stomach. "We found that TCEAL5 was differentially expressed among the three subtypes and was an independent prognostic factor, which implies that TCEAL5 is likely to be a new target for gastric cancer treatment." (PMID 40263929, 2025). "The TCEAL7 expression level was significantly lower in the gastric cancer cell lines comparing with the levels of TCEAL1, TCEAL3, TCEAL4, TCEAL5 and TCEAL8." (PMID 23372750, 2013). "A real-time quantitative PCR was performed on normal gastricepithelial cell line GES1 and gastric cancer cell lines including AGS, MKN45, MGC803, SGC7901 and HGC27 to determine the mRNA levels of TCEAL1, TCEAL3, TCEAL4, TCEAL5, TCEAL7 and TCEAL8." (PMID 23372750, 2013).
Huntington disease (1 paper, 2022). Huntington disease (HD) is a rare neurodegenerative disorder of the central nervous system characterized by unwanted choreatic movements, behavioral and psychiatric disturbances and dementia. "Upregulation of MEG3, TRIM4, and TCEAL5 were reported in different models of Huntington’s disease with an intracellular aggregation of mutant HTT, suggesting a link between PSEN1 ΔE9 and mutant HTT-induced transcriptomic changes." (PMID 36552881, 2022).
TCEAL5 also shares sentences with these, for which no sentence is quoted: ependymoma (1 paper).